DLAT (dihydrolipoamide S-acetyltransferase)
Diseases named in the same sentence as DLAT in open-access papers (continued):
Sharing a sentence is not in itself a finding about the gene and the disease.
non-small cell lung carcinoma (7 papers, 2023 to 2024). A group of at least three distinct histological types of lung cancer, including non-small cell squamous cell carcinoma, adenocarcinoma, and large cell carcinoma. "Dihydrolipoamide S-acetyltransferase and dihydrolipoamide S-succinyltransferase, key genes in cuproptosis, were proven to be associated with non-small cell lung cancer prognosis and metastasis." (PMID 39654205, 2024). "PM2.5-induced up-regulation of DLAT and dysregulation of glycolytic metabolism was found to facilitate non-small-cell lung cancer carcinogenesis." (PMID 38671021, 2024). "DLAT, or dihydrolipoamide S-acetyltransferase, has been reported to mediate glycolysis reprogramming in non-small cell lung cancer." (PMID 36835825, 2023). "Over expression of glycolytic gene DLAT, which promoted glycolysis but suppressed acetyl-CoA production and enhanced the malignancy of non-small cell lung cancer (NSCLC) cells." (PMID 36891150, 2023). "Dihydrolipoamide S-acetyltransferase and dihydrolipoamide S-succinyltransferase may serve as predictive markers for metastasis in non-small cell lung cancer." (PMID 39654205, 2024). "Increased glycolytic metabolism and PM2.5-activated DLAT overexpression have been shown to accelerate the development of non-small cell lung cancer, suggesting that DLAT may be the therapeutic marker of this type of cancer." (PMID 37424068, 2023).
pancreatic cancer (7 papers, 2022 to 2025). "In this study, we successfully used cuprotosis-related genes to establish a prognosis-related risk model for pancreatic cancer patients, which included three genes LIPT1, LIAS, and DLAT." (PMID 36117848, 2022). "The IHC assays demonstrated that DLAT was highly expressed in pancreatic cancer tissues." (PMID 37330494, 2023). "In addition, western blot analysis confirmed that the expression of DLAT was obviously increased in pancreatic cancer cells compared to in normal control cells." (PMID 36647100, 2023). "TSF@ES‐Cu NPs transport copper ions into pancreatic cancer cells to produce rich ROS, destroy copper homeostasis of cells, down‐regulate FDX1 protein level, and induce DLAT protein aggregation, thus leading to cuproptosis of cells." (PMID 40091480, 2025). "PDP1, DLAT, DBT, LIAS and LITP1 were determined to be markedly higher at mRNA levels in pancreatic cancer Capan-1, CFPAC-1, PANC-1, MIA PaCa-2, and COLO357 cells than in normal HPDE6-C7." (PMID 40367233, 2025). "We selected a normal human pancreatic ductal epithelial cell line (i.e., HPDE6-C7) and 4 pancreatic cancer cell lines (i.e., CFPAC-1, PANC-1, SW1990, and AsPC-1) to examine the expression of DLAT, LIPT1, and LIAS." (PMID 36090999, 2022). "KEGG pathway analysis revealed that DLAT was primarily correlated to TCA cycle and pancreatic cancer pathways, which was in accordance with the fact that cuproptosis was related to lipoylated TCA cycle proteins, further demonstrating the rationality and feasibility of our work." (PMID 37330494, 2023).
colon cancer (6 papers, 2022 to 2024). "A previous study reported that the glycolysis-related gene DLAT was associated with the prognosis of colon cancer." (PMID 36246586, 2022). "Additionally, copper ions were enriched in colon cancer, and Cu2+ bound to lipoacylated dihydrolipoamide S-acetyltransferase (DLAT), inducing DLAT heteromerization." (PMID 38658965, 2024).
colorectal cancer (6 papers, 2022 to 2025). A primary or metastatic malignant neoplasm that affects the colon or rectum. "DLAT plays a protective role in colorectal cancer, and its low expression is associated with poor prognosis in patients." (PMID 40276654, 2025). "DLAT knockdown also suppressed proliferation of other cancer cell types including SW480 (colorectal cancer) and HT1376 (bladder cancer cells)." (PMID 39885202, 2025). "The study revealed that, compared to normal tissues, genes FDX1, DLD, DBT, DLST, and DLAT were significantly downregulated in colorectal cancer tissues, while LIPT1, GCSH, and ATP7B genes were upregulated." (PMID 40276654, 2025).
prostate carcinoma (6 papers, 2023 to 2025). A carcinoma that arises from epithelial cells of the prostate gland. "Studies have shown that Elesclomol–Cu in prostate cancer can enhance cellular response to docetaxel by activating copper accumulation dependent on the DLAT/mTOR pathway (which occurs both in vitro and in vivo)." (PMID 41463095, 2025). "Moreover, cuproptosis improved chemosensitivity to docetaxel in prostate cancer cell lines by hindering autophagy via the dihydrolipoamide S-acetyltransferase (DLAT)/mammalian target of rapamycin (mTOR) pathway." (PMID 40066457, 2025). "A previous study showed that alternate killed prostate cancer by targeting the DLAT protein." (PMID 39574473, 2024).
clear cell renal cell carcinoma (5 papers, 2022 to 2024). "In parallel, DLAT expression was also found to be positively correlated with immune B cell infiltration and CD274 expression in clear cell renal cell carcinoma." (PMID 36203594, 2022). "The results demonstrated that ATP7B, DLAT, and LIAS were upregulated in the 786-O cell line, which represented human renal clear cell adenocarcinoma cell, compared to the HK-2 cell line; while DBT and PDHB were found to be downregulated in 786-O cells." (PMID 36092880, 2022). "In addition, DLAT, as a CRG, was used to predict the prognosis of clear cell renal cell carcinoma." (PMID 36246586, 2022).
colon adenocarcinoma (5 papers, 2022 to 2024). "Another study identified ANKZF1 and DLAT as glycolysis-related genes to predict the survival in colon adenocarcinoma patients." (PMID 35924040, 2022). "Furthermore, some bioinformatics analyses have proposed that seven glycolysis genes, including DLAT, can affect the prognosis of patients with colon adenocarcinoma and be used to construct a survival prediction model." (PMID 36949759, 2023).
esophageal cancer (5 papers, 2023 to 2025). A primary or metastatic malignant neoplasm involving the esophagus. "The results exhibited a high methylation level of DLAT in BLCA, esophageal carcinoma (ESCA), HNSC, and LIHC tissues compared to normal tissues." (PMID 39574473, 2024).
head and neck squamous cell carcinoma (5 papers, 2023 to 2024). A squamous cell carcinoma that arises from any of the following anatomic sites: lip and oral cavity, nasal cavity, paranasal sinuses, pharynx, larynx, and salivary glands. "However, the mRNA levels of DLAT were all significantly down-regulated in head and neck squamous cell carcinoma (HNSC) and kidney renal clear cell carcinoma (KIRC)." (PMID 36949759, 2023). "It has been found that mRNA levels of DLAT are significantly higher in tumor tissues of liver hepatocellular carcinoma and stomach adenocarcinoma compared to normal tissues, whereas they are lower in head and neck squamous cell carcinoma and kidney renal clear cell carcinoma." (PMID 38722401, 2024). "In comparison, DLAT was lowly expressed in 5 types of cancers: adrenocortical carcinoma (ACC), bladder urothelial carcinoma (BLCA), head and Neck squamous cell carcinoma (HNSC), kidney renal clear cell carcinoma (KIRC), and acute myeloid leukemia (LAML)." (PMID 39574473, 2024).
thyroid cancer (5 papers, 2022 to 2025). "For paired tumors and adjacent normal tissues in TGCA, DLAT was lowly expressed in COAD, HNSC, KIRC, Kidney renal papillary cell carcinoma (KIRP), and thyroid carcinoma (THCA) and highly expressed in six types of cancer." (PMID 39574473, 2024).
liver disease (4 papers, 2019 to 2025). "DLAT is a protein-coding gene associated with diseases, such as pyruvate dehydrogenase E2 deficiency and liver disease." (PMID 39388708, 2025).
melanoma (4 papers, 2022 to 2023). A malignant, usually aggressive tumor composed of atypical, neoplastic melanocytes. "In melanoma, the mutation frequency of DLAT genes is the highest among all cancers, with more than 4% higher than those frequencies of all other cancers." (PMID 36949759, 2023). "We found that the expression of FDX1, LIAS, LIPT1, DLD, DLAT, MTF1, and CDKN2A were significantly lower in melanoma than in normal tissues." (PMID 36824136, 2023). "CRGs with low and moderate CNV, such as PDHA1, DLAT, GLS, and LIAS, were overexpressed in CRC comparison to those in normal melanoma samples, whereas CRGs with high CNV, such as PDHB, were significantly increased in melanoma samples, implying that CNV may regulate CRG mRNA expression." (PMID 36824136, 2023).
Obesity (4 papers, 2023 to 2025). Accumulation of substantial excess body fat. "Since obesity is a significant risk factor for AS, activation of DLAT can indirectly prevent AS." (PMID 39519014, 2024). "DLAT activates the AMPK signaling axis in adipose tissue to produce heat, helping to suppress obesity." (PMID 39519014, 2024).
rectum adenocarcinoma (4 papers, 2023 to 2024). An adenocarcinoma arising from the rectum. "As per the findings, the expression of DLAT was significantly related to tumor stage in seven cancer types, namely, COADREAD, KIPAN, KIRC, LIHC, LUAD, rectum adenocarcinoma (READ), and THCA." (PMID 37199628, 2023).
acute myeloid leukemia (3 papers, 2022 to 2024). Acute myeloid leukemia (AML) is a group of neoplasms arising from precursor cells committed to the myeloid cell-line differentiation. "DLAT, encoding a subunit of the mitochondrial pyruvate dehydrogenase complex, was increased in acute myeloid leukemia compared with normal peripheral blood cells." (PMID 36092887, 2022). "The results indicated that DLAT expression levels were positively linked to CNV in nearly all cancer types, except for GBMLGG, acute myeloid leukemia (LAML), LGG, and UVM." (PMID 37199628, 2023).
glioblastoma (3 papers, 2015 to 2024). The most malignant astrocytic tumor (WHO grade IV). "Remarkably, however, except for DLAT in U87 cells, all other catalytic and regulatory components of PDHC as well as pyruvate transporters are expressed at similar ratios in HEK293 and glioblastoma cells." (PMID 26503465, 2015).
ovarian carcinoma (3 papers, 2022 to 2025). A malignant neoplasm originating from the surface ovarian epithelium. "We explored the potential of YY1, FDX1, DLD, DLAT, and PDHB to serve as non-invasive diagnostic markers of ovarian cancer." (PMID 36484005, 2022). "Following Elesclomol treatment of ovarian cancer cells, there was a notable increase in mitochondrial reactive oxygen species (ROS), a significant accumulation of the copper death marker protein DLAT, and a marked decrease in the lipoic acid synthesis-related protein FDX1." (PMID 41516324, 2025). "Bioinformatics analysis revealed that four core factors (lipoic acid pathway FDX1, DLD, DLAT, PDH), and transcription factor YY1 were highly expressed in ovarian cancer tissues and were significantly correlated with an unfavorable prognosis." (PMID 36484005, 2022). "The results of the cDNA expression profile analysis showed that four factors (i.e. FDX1, DLD, DLAT, PDHB) were highly expressed in the tumor tissues of ovarian cancer patients." (PMID 36484005, 2022). "We used an exosome database for screening and found that the levels of FDX1, DLD, DLAT, PDHB, and YY1 in peripheral blood exosomes from ovarian cancer patients were significantly higher than those in the normal controls." (PMID 36484005, 2022). "Our study revealed that the expression of four core factors of the lipoic acid pathway (i.e., FDX1, DLD, DLAT, and PDHB) was distinct between ovarian cancer patients and normal tissues and that it was significantly correlated with a poor prognosis inovarian cancer patients." (PMID 36484005, 2022). "In addition, the expression levels of YY1 in the tissue samples from ovarian cancer patients were significantly positively correlated with the expression levels of FDX1, DLD, DLAT, PDHB, and other genes." (PMID 36484005, 2022). "In conclusion, our study indicates that the detection of FDX1, DLAT, YY1 levels in the peripheral blood exosomes of patients with ovarian cancer can be used to quickly, accurately, and effectively predict the progress and prognosis of patients with ovarian cancer." (PMID 36484005, 2022).
pancreatic adenocarcinoma (3 papers, 2022 to 2023). "DLAT, LIPT1, and LIAS served as diagnostic biomarker in pancreatic adenocarcinoma." (PMID 36703728, 2022).
pyruvate dehydrogenase deficiency (3 papers, 2021 to 2023). A rare neurometabolic disorder characterized by a wide range of clinical signs with metabolic and neurological components of varying severity. "Moreover, pyruvate dehydrogenase deficiency, a disease characterized by primary lactic acidosis and neurological dysfunction, was related to DLAT gene mutation." (PMID 37330494, 2023). "Interestingly, this case also represents a phenotypic expansion of DLAT-related pyruvate dehydrogenase deficiency." (PMID 34645488, 2021).
renal carcinoma (3 papers, 2022 to 2024). A carcinoma arising from the epithelium of the renal parenchyma or the renal pelvis. "Moreover, DLAT mRNA levels were lower in renal cancer tissues than that in paracancerous tissues from the TCGA-KIRC, ICGC (RECA-EU) and GEO (GSE36895) databases." (PMID 37938155, 2023). "In vitro experiments showed that the expression of DLAT in normal renal cells (HK-2) was significantly higher than that in renal cancer cells (OS-RC-2 and 786-O), regardless of the mRNA or protein expression." (PMID 37938155, 2023).
adrenocortical carcinoma (2 papers, 2023 to 2024). "The results of the univariate Cox regression analysis showed that DLAT expressions had an adverse effect on the OS of patients with adrenocortical carcinoma (ACC), BLCA, BRCA, HNSC, kidney chromophobe (KICH), LGG, LIHC and PAAD (Hazard ratio>1, P < 0.05)." (PMID 36949759, 2023).
autoimmune disease (2 papers, 2023 to 2024). A disorder resulting from loss of function or tissue destruction of an organ or multiple organs, arising from humoral or cellular immune responses of the individual to their own tissue constituents. "Studies have revealed that DLAT plays an immunomodulatory role in some autoimmune diseases." (PMID 36949759, 2023). "Previous studies have confirmed that DLAT plays a role in autoimmune diseases, such as PBC, a liver-specific autoimmune disease." (PMID 36949759, 2023).
B-cell chronic lymphocytic leukemia (2 papers, 2022 to 2023). "A previous study showed an increase in DLAT expression in B cells in older patients with chronic lymphocytic leukemia." (PMID 37762710, 2023).
brain cancer (2 papers, 2022). A primary or metastatic malignant neoplasm affecting the brain. "Brain cancers (GBM and LGG) were found to potentially have a higher copper metabolism-related cell death compared to normal brain tissue because their anti-cuproptosis gene ATP7B was downregulated with pro-cuproptosis genes SLC31A1, FDX1, DLAT, and LIAS upregulated in cancer tissues." (PMID 36276096, 2022).
chronic apical periodontitis (2 papers, 2023 to 2026). Chronic form of periapical periodontitis. "We observed that the expression levels of the copper importer SLC31A1 and dihydrolipoamide S-acetyltransferase (DLAT) were positively correlated with bone loss in both human chronic apical periodontitis (CAP) tissues and mouse CAP models." (PMID 41629272, 2026).
colitis (2 papers, 2022 to 2025). Inflammation of the colon. "PA inhibited cuproptosis in the intestinal barrier of mice with colitis by reducing excess copper levels and DLAT oligomerization, as well as rescuing the loss of FDX1 and LIAS." (PMID 40969742, 2025). "Our study is the first to demonstrate the accumulation of copper in the colonic mucosa, resulting in the loss of Fe-S cluster-containing proteins FDX1 and LIAS and a reduction in DLAT oligomerization leading to cuproptosis in DSS-induced colitis mice." (PMID 40969742, 2025). "In DSS-induced colitis mice, the level of DLAT lipoylation was significantly reduced, but excess copper directly bound to and induced the oligomerization of lipoylated DLAT." (PMID 40969742, 2025). "We demonstrated that PA effectively inhibited cuproptosis in the colonic mucosa of colitis mice, as shown by the reduction in abnormally elevated copper levels in the colonic mucosa, restoration of FDX1, LIAS, and protein lipoylation levels, and decreased DLAT oligomerization." (PMID 40969742, 2025).
diffuse large B-cell lymphoma (2 papers, 2022 to 2023). "However, a large majority of cuproptosis-associated genes including FDX1, LIAS, LIPT1, DLD, DLAT, and PDHB acted as a low-risk indicator in Lymphoid neoplasm diffuse large B-cell lymphoma (DLBC)." (PMID 36105090, 2022). "Additionally, we found that DLAT expression was positively correlated with MSI in KIPAN, STAD, STES, and UCEC, but negatively correlated with MSI in BRCA, lymphoid neoplasm diffuse large B-cell lymphoma (DLBC), GBMLGG, HNSC, LUSC, PRAD, and THCA." (PMID 37199628, 2023).
liposarcoma (2 papers, 2022 to 2023). A usually painless malignant tumor that arises from adipose tissue. "The downregulation of DLAT has been associated with its chromosomal deletions in liposarcoma, thus suggesting that the chromosomal deletions of FDX1 and DLAT may affect their own expression levels." (PMID 36685880, 2022).
metastatic tumors (2 papers, 2024 to 2025). "Our findings revealed an increase in metabolic-related genes within the cancer cells, with the hub gene Dlat (Dihydrolipoamide S-Acetyltransferase) showing a significant association with the development of lung metastatic tumors." (PMID 39695088, 2024). "This, in turn, enhances the expression of lipoylated DLAT oligomers, thereby triggering cuproptosis and suppressing the progression of metastatic tumors." (PMID 40270362, 2025).
sarcopenia (2 papers, 2023 to 2025). Progressive decline in muscle mass due to aging which results in decreased functional capacity of muscles. "In this study, we also found that expression levels of DLAT was downregulated in the sarcopenia group." (PMID 37007946, 2023). "Our findings indicate the cuproptosis-related genes, PDHA1, DLAT, PDHB, and NDUFC1 are the diagnostic biomarker for sarcopenia, which provide evidence concerning the role of cuproptosis in sarcopenia." (PMID 37007946, 2023). "According to the results of ROC analysis, PDHA1, DLAT, PDHB, and NDUFC1 were selected as the potential promising diagnostic biomarkers of sarcopenia." (PMID 37007946, 2023). "The four hub genes (PDHA1, DLAT, PDHB, and NDUFC1) were included to construct a diagnostic model for sarcopenia." (PMID 37007946, 2023). "A total of four overlapping genes were extracted as the hub genes involved in sarcopenia and cuproptosis, which were PDHA1, DLAT, PDHB and NDUFC1." (PMID 37007946, 2023). "Intersection of DEGs, WGCNA and CRGs yielded four core genes (PDHA1, DLAT, PDHB, and NDUFC1) as potential biomarkers for the prediction of sarcopenia." (PMID 37007946, 2023). "A total of four possible hub genes of sarcopenia were screened, namely, PDHA1, DLAT, PDHB, and NDUFC1." (PMID 37007946, 2023). "The present study inferred the significance of mitochondrial dysfunction in the progression of sarcopenia, and the four cuproptosis-related genes, PDHA1, DLAT, PDHB, and NDUFC1, may serve as the potential targets for further therapeutic intervention." (PMID 37007946, 2023).
Sepsis (2 papers, 2023 to 2025). Sepsis is defined as life-threatening organ dysfunction caused by a dysregulated host response to infection. "The top five gene variables (MTF1, UBE2D2, DLAT, DLD, and ULK2) were selected as disease signature genes in the GLM model to construct a nomogram for predicting the incidence of sepsis-associated ALI." (PMID 38779731, 2025). "The expression of SLC31A1, CD274, ATOX1, MTF1, UBE2D1, DLD, and VEGFA was found to be upregulated, while that of DLST, UBE2D2, COX11, DLAT, GLS, FDX1, and ULK2 were significantly downregulated in patients with sepsis-associated ALI." (PMID 38779731, 2025).